LINC00265 (long independently transcribed non-coding RNA 265)
Synonyms: NCRNA00265-1; formerly NCRNA00265
Gene: Long non-coding RNA gene on chromosome 7 (39,733,122 to 39,794,745, forward strand). Ensembl gene ENSG00000188185.
Gene Ontology:
Molecular function: U4 snRNA binding
Biological process: formation of quadruple SL/U4/U5/U6 snRNP; spliceosomal tri-snRNP complex assembly
Cellular component: U4/U6 x U5 tri-snRNP complex; U6 snRNP
Diseases named in the same sentence as LINC00265 in open-access papers:
LINC00265 is named in the same sentence as 11 diseases in open-access papers, as found by Europe PMC text mining. Sharing a sentence is not in itself a finding about the gene and the disease. The quoted sentences say what the papers report.
acute myeloid leukemia (3 papers, 2020 to 2024). Acute myeloid leukemia (AML) is a group of neoplasms arising from precursor cells committed to the myeloid cell-line differentiation. "For example, studies have shown that the expression of linc00265 was increased in bone marrow and serum of acute myeloid leukemia (AML) patients, which was associated with poor overall survival." (PMID 35692754, 2022). "LINC00265 helps ZMIZ2 to stabilize β-catenin by acting as a sponge (and thereby inhibiting several miRNAs) in colorectal cancer, and it can be used to predict poor prognosis in acute myeloid leukemia patients." (PMID 32793593, 2020).
glioma (3 papers, 2022 to 2025). A benign or malignant brain and spinal cord tumor that arises from glial cells (astrocytes, oligodendrocytes, ependymal cells). "The forest plot shows that EPB41L4A.AS1, GDNF.AS1, HAR1A, LINC00237, SLC25A21.AS1, SNA13.AS1, and WDFY3.AS2 are the protective factors with HR < 1, while LINC00092, LINC00265, LINC00339, LINC00665, PAXIP1.AS2, SNHG16, SNHG9 and SOCS2.AS1 are risk factors with HR>1 in glioma patients." (PMID 35273128, 2022).
colorectal cancer (2 papers, 2020 to 2024). A primary or metastatic malignant neoplasm that affects the colon or rectum. "LINC00265 displays oncogenic activity in several cancers, including hepatocellular carcinoma, bladder cancer, and gastric and colorectal cancers." (PMID 38948024, 2024).
lung adenocarcinoma (2 papers, 2022 to 2024). A carcinoma that arises from the lung and is characterized by the presence of malignant glandular epithelial cells. "LINC00265 is upregulated in lung adenocarcinoma and is a prognostic biomarker of this cancer." (PMID 38948024, 2024).
osteosarcoma (2 papers, 2022 to 2024). A usually aggressive malignant bone-forming mesenchymal neoplasm, predominantly affecting adolescents and young adults. "Linc00265 has been shown to involve in osteosarcoma oncogenesis; however, the underlying mechanism is largely unclear." (PMID 35692754, 2022). "The results showed that linc00265 was highly expressed in osteosarcoma cell lines compared with HOB cells." (PMID 35692754, 2022). "To investigate the biological function of linc00265 in osteosarcoma cells, we transfected linc00265 plasmid and shR-linc00265 into MG63 and U2OS cells." (PMID 35692754, 2022). "In this study, we investigated the function of linc00265 in osteosarcoma cells, including cell viability, migration and invasion." (PMID 35692754, 2022). "In summary, linc00265 promoted cell viability, migration and invasion in osteosarcoma cells, indicating that linc00265 is an oncogene in osteosarcoma." (PMID 35692754, 2022). "Next, wound healing assays were conducted to examine the motility of osteosarcoma cells after linc00265 upregulation or downregulation." (PMID 35692754, 2022). "Osteosarcoma cells treated with shR-linc00265 plasmid displayed the lower expression of linc00265 compared with PSilencer transfection in both MG63 and U2OS cell lines." (PMID 35692754, 2022). "It is necessary to mention that in vivo mouse study will further validate the function of linc00265 in osteosarcoma development and progression." (PMID 35692754, 2022). "In the present study, we investigated the expression and biological functions of linc00265 in osteosarcoma cells." (PMID 35692754, 2022). "We found that linc00265 overexpression promoted viability, migration and invasion of osteosarcoma cells." (PMID 35692754, 2022). "Overexpression of linc00265 promotes osteosarcoma cell proliferation, migration, and invasion." (PMID 39062505, 2024). "Moreover, linc00265 was highly expressed in osteosarcoma patients and correlated with a poor prognosis." (PMID 35692754, 2022). "Taken together, linc00265 governs cell viability and colony formation in osteosarcoma cells." (PMID 35692754, 2022). "Increased linc00265 promoted closure in wound area in osteosarcoma cells." (PMID 35692754, 2022). "Thus, we aimed to determine the function and molecular insight of linc00265 in osteosarcoma progression." (PMID 35692754, 2022). "Taken together, targeting linc00265 is a promising approach for treating osteosarcoma patients." (PMID 35692754, 2022). "Moreover, we further explored the molecular mechanism of linc00265-mediated carcinogenesis in osteosarcoma." (PMID 35692754, 2022). "Moreover, we elucidated mechanistically the involvement of linc00265 in osteosarcoma." (PMID 35692754, 2022). "Together, inhibition of linc00265 could be a potential strategy for osteosarcoma therapy." (PMID 35692754, 2022). "We are wondering whether linc00265 upregulation could inhibit viability of osteosarcoma cells." (PMID 35692754, 2022). "Strikingly, linc00265 exerted its oncogenic function via regulating miR-485-5p and USP22 in osteosarcoma." (PMID 35692754, 2022). "Our results suggested that linc00265 upregulation increased the expression of USP22 at mRNA and protein levels, and linc00265 downregulation attenuated the USP22 expression levels in osteosarcoma cells." (PMID 35692754, 2022). "Importantly, linc00265 exerts its oncogenic function by regulating the expression levels of miR-485-5p and USP22 in osteosarcoma." (PMID 39062505, 2024). "Our study demonstrated that linc00265 promoted cell viability, migration and invasion via targeting miR-485-5p/USP22 axis in osteosarcoma, suggesting that linc00265 might be a useful target for osteosarcoma therapy." (PMID 35692754, 2022). "The role of linc00265 in osteosarcoma has not been fully investigated." (PMID 35692754, 2022).
acute lymphoblastic leukemia (1 paper, 2024). Leukemia with an acute onset, characterized by the presence of lymphoblasts in the bone marrow and the peripheral blood. "Interestingly, LINC00265 has been also shown to promote metastasis of acute lymphoblastic leukemia by regulating STAT3 signaling." (PMID 38948024, 2024).
lung carcinoma (1 paper, 2024). "They provide insights into the mechanism underlying LINC00265 activity in lung tumorigenesis, and help to identify potential targets for lung cancer therapy." (PMID 38948024, 2024). "Collectively, our functional analyses revealed an important role of LINC00265 in the development of lung cancer." (PMID 38948024, 2024). "Taken together, these results suggest that LINC00265 may play a role in the tumorigenesis of lung cancer and may represent a novel prognostic biomarker." (PMID 38948024, 2024). "However, how LINC00265 functions in lung cancer remains elusive." (PMID 38948024, 2024). "We next examined LINC00265 expression in different NSCLC cell lines and in lung cancer tissue by RT-qPCR analysis." (PMID 38948024, 2024). "We found that LINC00265 binds to and stabilizes SIN3A protein in lung cancer cells, thus identifying a novel partner for this LncRNA." (PMID 38948024, 2024). "Thus, targeting LINC00265 could be a potential strategy for treatment of lung cancer." (PMID 38948024, 2024). "Therefore, this expression profile of autophagy-related proteins is similar as observed in LINC00265-knockdown cells, suggesting that LINC00265 and SIN3A may function together to regulate lung cancer development." (PMID 38948024, 2024).
cancer (3 papers, 2022 to 2024). A tumor composed of atypical neoplastic, often pleomorphic cells that invade other tissues. "LINC00265 has been linked to the progression of various cancers, including HCC." (PMID 35511171, 2022). "Since there exist potential pathways linking apoptosis and autophagy in cancer, we examined how LINC00265-knockdown affects autophagy in NSCLC cell lines." (PMID 38948024, 2024). "Several studies have uncovered that linc00265 exerts tumor promotive functions in a number of cancer types." (PMID 35692754, 2022). "Indeed, LINC00265 has been shown to promote cell proliferation and viability in a number of cancers by interacting with other non-coding RNAs and key signaling pathways such as Epidermal Growth Factor (EGF) and Wnt/β-catenin." (PMID 38948024, 2024). "This suggests that LINC00265 plays a role in the migration and invasion of NSCLC cells and that it may function as an oncogene to promote tumorigenesis or cancer progression." (PMID 38948024, 2024).
tumor (3 papers, 2022 to 2024). "Given that better stability is an essential prerequisite for tumor biomarkers, we sought to assess the stability of LINC00265, LINC00467, UCA1, and SNHG1 in the isolated plasma exosomes." (PMID 36276083, 2022). "Evidence has revealed that linc00265 is critically involved in carcinogenesis and tumor progression in multiple type cancers." (PMID 35692754, 2022). "In summary, this study shows that upregulation of LINC00265 in LUAD leads to reduced overall survival rate in patients and that inhibition of LINC00265 can prevent tumor progression." (PMID 38948024, 2024).
LINC00265 also shares sentences with these, for which no sentence is quoted: bladder cancer (1 paper); hepatocellular carcinoma (1).